MSH6 (mutS homolog 6)
Diseases named in the same sentence as MSH6 in open-access papers (continued):
Sharing a sentence is not in itself a finding about the gene and the disease.
adenocarcinoma (26 papers, 2014 to 2026). A common cancer characterized by the presence of malignant glandular cells. "A recent study has demonstrated that IHC has a low sensitivity in identifying pathogenic MSH6-mutations, as almost 24% of adenocarcinomas in carriers of pathogenic MSH6 mutations showed normal staining of this gene." (PMID 24790682, 2014). "Three of the markers: GPR56, LY6G6D/F and SLCO1B3 had significantly higher expression in proximal adenocarcinomas and were positively correlated with mismatch repair protein expression, i.e. PMS2 and MSH6 with all three, and PMS1 with LY6G6D/F." (PMID 26894861, 2016).
infection (9 papers, 2013 to 2026). The state of being infected such as from the introduction of a foreign agent such as serum, vaccine, antigenic substance or organism. "Furthermore, studies using mouse genetic models found that Dyrk1a plays an important role in mature B-cell function in response to infection or vaccination by regulation of class-switch recombination mediated by phosphorylation of mutS homolog 6 (MSH6) protein." (PMID 37900285, 2023). "MSH6 expression varies among GC cell lines and showed a modest negative correlation with ERBB2 expression under HV-HP infection in the N87 cell line (t-value= –3.498, p = 0.0395)." (PMID 40642068, 2025).
breast (5 papers, 2021 to 2024). "Furthermore, they performed genomic sequencing on tumors before (pituitary) and after temozolomide treatment (liver) and found a MSH6 mutation in the TMZ-treated liver metastasis." (PMID 36157469, 2022).
genetic disorders (5 papers, 2016 to 2025).
digestive system cancer (3 papers, 2020 to 2022). A primary or metastatic malignant neoplasm involving any part of the digestive system. "Genetic content of identified variants regarding mononucleotide repeats in MLH1-/PMS2-/MSH6- digestive system cancer cases." (PMID 36387226, 2022). "Detailed overview and significance of MMR/HRR variants observed in MLH1-/PMS2-/MSH6- digestive system cancer cases." (PMID 36387226, 2022). "Further studies performing CNV analysis as well as whole exome or even whole genome sequencing of MLH1-/PMS2-/MSH6- digestive system cancers are necessary to fully understand the mutational landscape of these cases." (PMID 36387226, 2022). "The additional MMR/HRR mutations we could detect in our MLH1-/PMS2-/MSH6- cases could play a mechanistic role in the loss of MSH6 expression in already MLH1/PMS2-deficient digestive system cancers by paving the way for further mutations in the MSH6 gene." (PMID 36387226, 2022). "If further studies with larger cohorts can prove the clustering of mutations in DNA-repair related genes in MLH1-/PMS2-/MSH6- digestive system cancers, this peculiar immunophenotype could immediately trigger additional NGS-testing for HRR mutations as basis for therapy." (PMID 36387226, 2022). "MMR immunoexpression and molecular characterization of MLH1-/PMS2-/MSH6- digestive system cancer cases." (PMID 36387226, 2022). "To the best of our knowledge, we are the first group to specifically focus on the abnormalities in DNA repair of MLH1-/PMS2-/MSH6- digestive system cancer cases." (PMID 36387226, 2022). "It seems that MSH6 and EXO1 genetic mutations play an important role in gastrointestinal tract cancer with the EMAST+/MSI-H phenotype." (PMID 32120855, 2020). "Clinicopathological features MLH1-/PMS2-/MSH6- digestive system cancer cases." (PMID 36387226, 2022). "Of course, our findings are limited by the rarity of MLH1-/PMS2-/MSH6- digestive system cancers." (PMID 36387226, 2022).
cardiovascular disease (2 papers, 2019 to 2024). "However, the association of MSH6 with cardiovascular disease is still poorly explored, and we cannot speculate whether the possible mechanisms of action are similar to the mechanisms above of tumorigenesis." (PMID 39170695, 2024).
CNS tumors (2 papers, 2012 to 2024).
autosomal recessive inherited disease (1 paper, 2022).
MSH6 also shares sentences with these, for which no sentence is quoted: Peutz-Jeghers syndrome (8 papers); juvenile polyposis syndrome (7); hereditary pancreatitis (5); Li-Fraumeni syndrome (5); bladder tumors (4); esophageal cancer (4); hematological malignancies (4); autosomal dominant inherited disorder (3); colonic polyps (3); digestive tumour (3); endometrioid ovarian cancer (3); serous carcinoma (3); stomach cancer (3); triple-negative breast carcinoma (3); Ataxia (2); brain cancer (2); Breast invasive carcinoma (2); carcinosarcoma (2); childhood leukemia (2); clear cell renal cell carcinoma (2); Corticotroph Adenomas (2); DICER1 syndrome (2); duodenal cancers (2); head and neck squamous cell carcinoma (2); Hereditary breast cancer (2); hereditary diffuse gastric cancer (2); Immunodeficiency (2); leukemia (2); liposarcoma (2); metastatic colorectal cancer (2).
A further 124 diseases each share a sentence with MSH6 in 2 papers or fewer.